MIR4680 (microRNA 4680)
Synonyms: hsa-mir-4680
Gene: MicroRNA gene on chromosome 10 (110,898,090 to 110,898,155, forward strand). Ensembl gene ENSG00000284482.
Homologues: Orthologues: chimpanzee MIR4680 (100% identical).